APP (amyloid beta precursor protein)
Diseases named in the same sentence as APP in open-access papers (continued):
Sharing a sentence is not in itself a finding about the gene and the disease.
dementia (continued). "Although, in the case of DS, association with early-onset dementia is related to increased amyloid precursor protein (APP) resulting from trisomy of all or part of chromosome 21, multiple genetic and environmental factors likely contribute to increased AD susceptibility." (PMID 36102617, 2022). "Dementia is also associated with the APP, PS1 (presenilin 1), and PS2 genes." (PMID 36497027, 2022). "APP is most abundant in neurons and abnormal processing of APP is associated to senile dementia." (PMID 35754840, 2022). "For example, three copies of APP in Down’s Syndrome as well as local duplications and triplications are causative of dementia." (PMID 35360155, 2022). "Dementia is also caused by mutations in APP (amyloid precursor protein)." (PMID 36497027, 2022). "However, mutations of the APP gene are known to contribute to the early onset of dementia in familial AD (FAD) and is key to Aβ plaque formation and neurodegeneration in sporadic and FAD." (PMID 34362198, 2021). "Stress can induce the generation of APP, hyperphosphorylation of tau, NFTs, Aβ peptide, APs, oxidative stress, cognitive dysfunction, synaptic loss, neuronal loss, inflammatory mediator expression, and dementia in AD pathogenesis." (PMID 30837843, 2019). "This increased dementia risk is driven by the overexpression of genes on chromosome 21, in particular the amyloid precursor protein (APP) gene; deposits of its protein product, amyloid-β, are a characteristic feature of AD and are found in the brains of adults with full trisomy 21 by the mid-30s." (PMID 30503169, 2019). "Additionally, increased seizure risk has been documented in patients with APP duplication and in Down syndrome (DS) individuals (carrying 3 copies of the APP gene) with dementia (Menéndez, 2005)." (PMID 28392767, 2017). "Recent proteomic studies support the use of multianalyte profiling, e.g. subsets of 4–5 plasma proteins, either closely related to the amyloid protein precursor (APP) and tau protein and inflammation, or lipids associated with cell membrane integrity for diagnosing and even predicting dementia." (PMID 29077013, 2017). "This evidence emphasizes the pathogenic role of APP processing in familial human dementias." (PMID 25247712, 2014). "The amyloid cascade hypothesis posits that processing of APP produces Aβ, which then aggregates and forms fibrils, giving rise to synaptotoxicity and eventually causing dementia." (PMID 24682783, 2014). "Familial dementias are caused by mutations in APP and genes that regulate APP processing." (PMID 23451158, 2013). "However, recent data suggest that these dementias share pathogenic mechanisms involving synaptic-toxic APP metabolites distinct from Aβ." (PMID 23451158, 2013). "Familial dementia is also caused by mutations in genes that regulate APP processing." (PMID 22537414, 2012). "Although dementias due to APP/PSEN1/PSEN2 mutations are classified as familial Alzheimer disease (FAD) and those due to mutations in BRI2/ITM2B as British and Danish dementias (FBD, FDD), data suggest that these diseases have a common pathogenesis involving toxic APP metabolites." (PMID 23217200, 2012). "Similarly, the APP A673V mutation near the β-secretase site of APP has been shown to be associated with AD type of dementia and, consistent with an autosomal recessive pattern of inheritance, is pathogenic only in a homozygous state." (PMID 19468344, 2009). "Altogether, these data suggest synergism between APP/amyloid-β imbalance and mitochondrial damage in causing neurodegeneration with age, and imply, at least partially, a causative role for mitochondria dynamics in the insurgence of dementia-like manifestations." (PMID 38616258, 2024). "The imbalance of brain endothelial APP between its production and clearance could lead to Aβ deposition on vessels in the CNS and poses a high risk to individuals of developing cerebrovascular disease and dementia, including AD." (PMID 38328307, 2023).
dementia (continued). "However, the fact that increased APP dosage is causative of familial forms of the disease supports the idea that reducing APP expression could reduce the risk of dementia and potentially slow progression–at least for fAD." (PMID 35360155, 2022). "Notably, the age of clinical dementia diagnosis occurs slightly later in individuals who have DS, compared with those who have early-onset familial AD caused by duplication of APP (i.e., with three copies of WT APP)." (PMID 35835549, 2022). "Analogous to how carriers of the Icelandic (A673T) APP mutation have a reduced risk for AD, we speculate that mutations in a GxxxG motif, such as our G29A, could serve as another way to lessen Aβ deposition and thus subsequent neurodegeneration and dementia." (PMID 33571524, 2021). "To confirm these findings, to test whether these APP metabolic changes are also evident in heterozygous Apps/h rats, which genocopy the condition that causes dementia in humans, and to determine whether sex influences these alterations, we analyzed a new cohort of Apph/h, Apps/h and Apps/s rats." (PMID 32022689, 2020). "The evidence that a pathogenic APP mutation causes an early enhancement of BAD‐Glu suggests that alterations of BACE1 processing of APP in glutamatergic synaptic vesicles could contribute to dementia." (PMID 31496118, 2019). "Furthermore, this result suggests that APP is abnormally cleaved in DS subjects with dementia and indicates that the underlying pathophysiology of DS with dementia might be different from that of non-DS patients with AD." (PMID 28144219, 2016). "In general, while mutant APP transgenic mice develop robust amyloid deposition, synaptotoxic features and memory impairments, none of them reproduces tau-containing neurofibrillary tangles, the hallmark pathology of AD which most closely correlates with dementia." (PMID 26528151, 2015). "Mutations in these genes confer specific phenotypic profiles to patients with dementia: amyloidogenic pathology associated with APP, PSEN1, and PSEN2 mutations and tauopathy associated with MATP mutations, representing the two major pathogenic hypotheses for AD." (PMID 22482072, 2012). "Akkermansia muciniphila itself as well as its metabolites have been proven to alleviate dementia-like symptoms in APP/PS1 mice and 5×FAD mice." (PMID 40860878, 2025). "Significant dockings (with confidence scores greater than 0.7) were identified in these experiments involving OMdP in bEVs with several dementia-related proteins, including AD-neuropathological markers, such as APP, PrP, TAU, and PSEN1." (PMID 41237903, 2025). "Our IPA network analysis revealed APP–tau interactions in DS brains, suggesting that their toxic synergy occurs well before clinical dementia onset." (PMID 41269384, 2025). "The limit of typical APP sequence leads to an increase in total Aβ and ultimately to the rise in Aβ accumulation, which leads to dementia and neuropathology of AD." (PMID 39980585, 2025). "Aβ, generated through proteolytic cleavage of amyloid precursor protein (APP) by β- and γ-secretases, is widely recognized as a major contributor to neuronal impairment and, ultimately, dementia." (PMID 41050403, 2025). "SFPQ levels were found to be decreased in the postmortem brains of patients with rapidly progressing AD (rpAD), sporadic Creutzfeldt–Jakob disease (sCJD, a rapidly progressive form of dementia), and in 3xTg (amyloid precursor protein [APP]/PS1/Tau) mice." (PMID 39949834, 2025). "Beyond APOE4, we found that the metabolite–dementia associations are also modified by other common AD/ADRD risk variants implicated in cholesterol homeostasis, mitochondrial function, APP production and extracellular matrix integrity." (PMID 40855194, 2025). "An intriguing observation is that trisomy 21 also significantly contributes to an increased dosage effect of the APP gene, leading to AD and dementia." (PMID 38790243, 2024).
dementia (continued). "Searching for other dementia cases resulted in the identification of APP p.A713T in one DLB case and PSEN1 p.A79V in a possible AD case according to ADSP diagnosis criteria." (PMID 39606324, 2024). "Mutations in ITM2B (which encodes the BRI2 precursor protein) that are associated with rare familial Danish and British dementias resembling AD result in decreased BRI2 protein levels and, consequently, increased APP processing." (PMID 37307834, 2024). "For example, age-related demethylation in the promoter regions of the amyloid precursor protein (APP) gene due to aging leads to the concentration of Aβ peptides in the brain, ultimately resulting in dementia." (PMID 39766866, 2024). "Currently, some dementia-related genes (such as APOE, MPKA, and APP/PS1) have been found to have good clinical diagnostic value." (PMID 37189611, 2023). "APP is a transmembrane protein whose pathological cleavage into aggregate forms of Aβ lead to the formation of senile plaques within AD and other dementia." (PMID 37531953, 2023). "An interesting link to monogenic dementia has recently been revealed, as DCTN1 has been found in a yeast two-hybrid screen to directly interact with APP and tau (encoded by MAPT), suggesting that these three proteins are linked at a molecular level." (PMID 37330543, 2023). "In particular, PRNP, DNMT1 and APP play a role not only in the EOD but also in several other forms of dementia and brain diseases." (PMID 37819683, 2023). "AD is a progressive type of dementia characterized by the aggregation into β-sheets of the amyloid β peptide (Aβ), which is derived from the cleavage of the amyloid precursor protein (APP)." (PMID 37764469, 2023). "In the rodent model of APP/PS1 dementia, the reported level of Aβ in the blood is in the ∼10 to 70 ng/ml range." (PMID 37030503, 2023). "Amyloid Aβ peptides, which accumulate in senile plaques in dementia, and the amyloid precursor protein (APP), are expressed in megakaryocytes, stored in platelet α-granules and released upon platelet activation." (PMID 36672180, 2023). "On Day 5 in MWM, APP/PS1 mice had poorer performance than non-dementia control, as evidenced by a decreased number of platforms crossing (p < 0.001), and reduced time in the target quadrant (p < 0.001)." (PMID 37063260, 2023). "By reducing mTOR activity and directly activating ULK1, AMPK also leads to the formation of autophagosomes and the degradation of Tau and APP, thus achieving the purpose of treating dementia." (PMID 37189611, 2023). "We previously demonstrated that DNMT1 mRNA levels are not regulated in buffy coat samples from patients with AD, whereas DNMT3a expression is downregulated in buffy coats from dementia patients and in the brain of saline-treated APP/BIN1/COPS5 AD mice." (PMID 36432638, 2022). "The behavioral and psychological symptoms of dementia commonly presented by patients have also been observed in several transgenic mouse models of AD-related pathology, including APP/PS1, Tg2576, 3xTg-AD, 5xFAD, and APP23." (PMID 35269588, 2022). "We found a significant increase in the level of APP Tyr phosphorylation in the majority of fibroblasts from AD patients when compared to healthy donors, as well as patients with other dementias." (PMID 33466666, 2021). "In one study, seizures were reported in 57% of affected individuals with dementia carrying APP duplication." (PMID 33741601, 2021). "AD is the most common form of dementia which is characterized by neurodegenerative and neuronal death from neurotoxicity, β-amyloid (Aβ) plaques, a product of the membrane-bound amyloid precursor protein (APP) cleaved by β-secretase." (PMID 34065080, 2021). "PPI network that demonstrated proteins such as PSEN1, PSEN2, APP, MAPT, and C9orf72 had abundant interactions with other proteins, which was consistent with the important roles of these dementia pathogenic genes." (PMID 34720994, 2021).
dementia (continued). "At best, the 3xTg-AD model is representative of early-onset familial AD caused by genetic mutations in APP and PSEN1, which account for an estimated 1% or less of all AD-related dementia cases." (PMID 33472690, 2021). "Seizures and epilepsy are also more frequently observed in DS individuals (who carry APP overexpression by virtue of trisomy 21 and who universally develop AD neuropathological hallmarks and dementia by age 40–55)." (PMID 33741601, 2021). "DYRK1A phosphorylates key substrates involved in AD and dementia: Tau, septin 4, amyloid precursor protein (APP), presenilin 1, neprilysin, Munc18-1, α-synuclein, RCAN1, and β-tubulin." (PMID 34205123, 2021). "All patients carrying variants in APP, CSF1R, ITM2B (p.Ile251Val), and NOTCH3 genes showed a family history for dementia." (PMID 33770234, 2021). "Although beta-secretase (BACE1) expression and its enzymatic activity were reported to increase in most sporadic AD patients, APP full-length protein and γ-secretase proteolytic activity remained unchanged (compared to non-dementia controls)." (PMID 33003364, 2020). "The conventional interpretation of the AD‐like dementia in DS patients is that it is due to the APP gene on chromosome 21; triplicate copies of the APP gene facilitate amyloid‐beta accumulation and development of AD in DS patients." (PMID 31981470, 2020). "The identification of molecular mechanisms responsible for vasoprotective properties of endothelial APP may have an impact on clinical efforts to preserve and protect healthy vasculature in patients at risk of the development of cerebrovascular disease and dementia including AD and CAA." (PMID 33228083, 2020). "Another important constituent of FB bark are phytosterols as they play imperative role in modulating amyloid precursor protein (APP) processing and amyloid beta plaque formation which are molecular activities contributing towards dementia." (PMID 32210162, 2020). "We detected an APP primary transcript derived circRNA from human brain samples of AD patients and non-dementia controls." (PMID 33003364, 2020). "Several APP mutations cause familial Alzheimer’s disease (AD), while the Icelandic APP mutation near the BACE1-cleavage site protects from sporadic dementia, emphasizing APP’s role in dementia pathogenesis." (PMID 32022689, 2020). "It is well recognized that the complex pathology of dementias such as AD means it cannot be adequately studied in a single animal model, as they are largely based on a single hypothesis, and usually rely on rare genetic mutations detected in AD (APP, BACE, presenilin) or FTD (tau) patients." (PMID 31884477, 2020). "Synaptic transmission is known to be disturbed in the hippocampus of many APP- and tau-based mouse models of dementia." (PMID 29484523, 2019). "In contrast to APP-based mouse models of dementia, there are relatively few studies of synaptic plasticity in tau-based mouse models of dementia." (PMID 29484523, 2019). "As a result of life-long overexpression of the APP and DYRK1a genes, DS individuals suffer from AD-related dementia in the vast majority of the cases over 40y." (PMID 30389461, 2019). "Here, we showed that plasma ATG5 levels were increased both in APP Tg mice and human patients with dementia or MCI compared to healthy control subjects." (PMID 30894637, 2019). "In contrast, humans carrying the Icelandic APP variant, which codes for an APP protein that is inefficiently cleaved by BACE1, are protected from dementia and normal cognitive decline." (PMID 31496118, 2019). "Individuals with duplicated APP have dementia onset that is fully penetrant, between 39 to 64 years of age." (PMID 28993310, 2017). "Mutations in the amyloid precursor protein (APP) and the presenilin (PSEN) genes clearly demonstrated that dysfunctions in APP processing are causative of dementia in these cases." (PMID 27770234, 2016).
dementia (continued). "Although Aβ deposition is considered a signature lesion for AD, it also occurs in Down's syndrome, possibly due to triple multiplication of amyloid precursor protein (APP), as well as in certain cases of dementia with Lewy bodies." (PMID 26538832, 2015). "Effects of the trisomy of APP and other segments of human chromosome 21 on development of intellectual disability (independently of dementia), and on presence of early clinical dementia." (PMID 26648852, 2015). "Development of dementia in DS patients is the result of overproduction of toxic Aβ species as a direct consequence of the triplication of the APP gene." (PMID 26388726, 2015). "This type of dementia is characterized by the accumulation of misfolded beta-amyloid (Aβ), a protein produced from the cleavage of the amyloid precursor protein (APP), and neurofibrillary tangles (aggregates of hyperphosphorylated tau protein) in the brain." (PMID 26301043, 2015). "Overall our results consolidate and refine the importance of Y682 in APP normal functions from an animal model of premature aging and dementia." (PMID 26690411, 2015). "Autosomal dominant AD (ADAD) is a rare form of AD, caused by mutations in genes encoding presenilin-1 (PSEN1), presenilin-2 (PSEN2), or amyloid precursor protein (APP) and leading to young onset dementia." (PMID 25922840, 2015). "We have successfully modeled mixed dementia by combining the HHcy model of VaD with the amyloid-depositing APP/PS1 transgenic mouse." (PMID 24991237, 2014). "Despite the pathologic changes, the age of onset (AOO) of dementia varies, suggesting that factors other than trisomy of APP in DS are important." (PMID 24462566, 2014). "Although mutations in APP and genes that regulate processing of APP, such as PSENs and BRI2/ITM2B, cause dementias, the normal function of APP in synaptic transmission, synaptic plasticity and memory formation is poorly understood." (PMID 25247712, 2014). "Recent findings suggest that products of BACE1-processing of APP (predominantly ß-CTF) trigger several pathological features related to human dementias both in a mouse model of FDD and human neurons derived from familial and sporadic AD." (PMID 23451158, 2013). "Cases caused by APP/PSEN mutations are classified as FAD and those caused by mutations in BRI2/ITM2b as FDD or Familial British dementia (FBD)." (PMID 23451158, 2013). "Proteolytic processing of brain proteins, such as tau, APP, and α-synuclein, is a key pathological event in dementias." (PMID 22779024, 2012). "The prevailing pathogenic model for dementias caused by mutations in APP and genes that regulate APP processing (PSEN1, PSEN2 and BRI2/ITM2b) posits that amyloid peptides trigger dementia." (PMID 23217200, 2012). "In the Swedish familial form of AD, an APP mutation at the β-site makes the protein a more efficient substrate for BACE, resulting in early onset dementia and a more rapid disease progression." (PMID 22481915, 2012). "Pathogenic mutations in APP, PSEN1, PSEN2, MAPT and GRN have previously been linked to familial early onset forms of dementia." (PMID 22312439, 2012). "Mutations in the APP, PSEN1, PSEN2, and MAPT genes give rise to well-characterized differential neuropathological and clinical phenotypes of dementia." (PMID 22482072, 2012). "Mutations in any of 4 genes are causative of early onset dementias due to either AD (presenilin 1 [PSEN1], presenilin 2 [PSEN2], and amyloid precursor protein [APP]) or prion disease (prion protein gene, PRNP)." (PMID 21193246, 2012). "From a molecular point of view, we need a focused effort to fully understand the functions of APP and Aβ and to answer the two key questions: does Aβ in fact influence tau phosphorylation and, if yes, does tau phosphorylation in fact lead to dementia?" (PMID 22506132, 2012).